HCCAT5 (hepatocellular carcinoma associated transcript 5)
Synonyms: HTA; FJ222407
Gene: Long non-coding RNA gene on chromosome 16 (73,092,349 to 73,099,337, forward strand). Ensembl gene ENSG00000260880.
Diseases named in the same sentence as HCCAT5 in open-access papers:
HCCAT5 is named in the same sentence as 8 diseases in open-access papers, as found by Europe PMC text mining. Sharing a sentence is not in itself a finding about the gene and the disease. The quoted sentences say what the papers report.
hepatocellular carcinoma (2 papers, 2024 to 2025). A malignant tumor that arises from hepatocytes. "Skeletal muscle lncRNAs upregulated by aging included HCCAT5, a hepatocellular carcinoma‐associated transcript, and MIR503HG, which has been implicated in endothelial‐to‐mesenchymal transition in vascular disease." (PMID 38297807, 2024). "The capacity to induce tumor formation in nude mice and alter the expression levels of certain genes associated with apoptosis indicates the potential significance of HCCAT5 in the advancement and progression of hepatocellular carcinoma, with its mechanism potentially linked to apoptosis." (PMID 40842702, 2025). "HCCAT5 stands out even more in the diagnosis of hepatocellular carcinoma due to its unique low expression rate in other cancer types." (PMID 40842702, 2025). "Analysis of gene expression has revealed that HCCAT5 exhibits specific expression patterns in particular tumor types, with a notably elevated expression level observed in hepatocellular carcinoma." (PMID 40842702, 2025). "This suggests that the upregulation of HCCAT5 gene transcription is crucial for the viability of hepatocellular carcinoma cells and is a consistent occurrence during tumorigenesis." (PMID 40842702, 2025). "RT-PCR demonstrated that HCCAT5 exhibited specific expression in particular tumor types, with a notably high expression level observed in hepatocellular carcinoma." (PMID 40842702, 2025). "The knockdown experiment provided insights into the specific expression characteristics and cancer-promoting effect of HCCAT5, indicating its potential involvement in the development of hepatocellular carcinoma." (PMID 40842702, 2025). "Inhibition of endogenous HCCAT5 expression in malignant HepG2 hepatocytes using small interfering RNA results in the suppression of hepatocellular carcinoma cell proliferation." (PMID 40842702, 2025).
Gastric Tumors (1 paper, 2025). "The current study evaluated the expression of lncRNA HCCAT5 in primary gastric tumors as well as in adjacent noncancerous tissues." (PMID 40842702, 2025).
cancer (1 paper, 2025). A tumor composed of atypical neoplastic, often pleomorphic cells that invade other tissues. "HCCAT5 exhibits a distinct expression profile in cancer, particularly in GC." (PMID 40842702, 2025). "The expression pattern of HCCAT5 suggests that it could serve as a promising molecular target for the advancement of novel cancer therapies while minimizing the potential for adverse reactions." (PMID 40842702, 2025).
tumor (1 paper, 2025). "The present study first demonstrated that there is a high level of HCCAT5 expression in tumor tissues in comparison to peripheral noncancerous tissues of patients with GC, suggesting a potential oncogenic role for HCCAT5 in these individuals." (PMID 40842702, 2025).
HCCAT5 also shares sentences with these, for which no sentence is quoted: diffuse large B-cell lymphoma (1 paper); follicular lymphoma (1); gastric cancer (1); liver (1).